PAQR4 (progestin and adipoQ receptor family member 4)
Description:
Plays a role in maintaining adipose tissue function through the regulation of ceramide levels. Mediates the stability of ceramide synthetases, CERS2 and CERS5, and their activities (Probable).
Synonyms: FLJ30002
Tractability: Antibody: UniProt predicts a signal peptide or a membrane-spanning region. PROTAC: ubiquitination databases record sites on it; its protein half-life has been measured.
Gene: Protein-coding gene on chromosome 16 (2,969,242 to 2,973,484, forward strand). Ensembl gene ENSG00000162073.
Subcellular location: Golgi apparatus membrane
Subcellular location (Human Protein Atlas): Vesicles
Gene Ontology:
Molecular function: molecular adaptor activity
Biological process: protein stabilization; regulation of ceramide biosynthetic process
Cellular component: Golgi membrane; membrane
Genetic constraint (gnomAD): Loss-of-function variants: 26 observed, 20.93 expected, observed/expected ratio (o/e) 1.24, 90% interval 0.91 to 1.71. The upper end of that interval is the gene's LOEUF score, 1.71, which puts it in group 6 of 6, group 1 being the genes least tolerant of losing a copy. Missense variants: 400 observed, 373.88 expected, observed/expected ratio (o/e) 1.07, 90% interval 0.99 to 1.16. Synonymous variants: 193 observed, 165.65 expected, observed/expected ratio (o/e) 1.17, 90% interval 1.03 to 1.31.
Homologues: Orthologues: chimpanzee PAQR4 (100% identical), macaque PAQR4 (99% identical), mouse Paqr4 (96% identical), rat Paqr4 (96% identical), guinea pig PAQR4 (96% identical), dog PAQR4 (72% identical), tropical clawed frog paqr4 (64% identical), zebrafish paqr4a (62% identical), zebrafish paqr4b (57% identical), Drosophila melanogaster CG33203 (39% identical), Caenorhabditis elegans K11C4.2 (20% identical). Paralogues in human: PAQR6 (26% identical), PAQR5 (24% identical), PAQR7 (23% identical), ADIPOR1 (22% identical), PAQR8 (22% identical), ADIPOR2 (21% identical), PAQR3 (21% identical), PAQR9 (19% identical), MMD (14% identical), MMD2 (13% identical).
Diseases named in the same sentence as PAQR4 in open-access papers:
PAQR4 is named in the same sentence as 33 diseases in open-access papers, as found by Europe PMC text mining. Sharing a sentence is not in itself a finding about the gene and the disease. The quoted sentences say what the papers report.
prostate carcinoma (9 papers, 2020 to 2025). A carcinoma that arises from epithelial cells of the prostate gland. "Interestingly, the up-regulation of PAQR4 was revealed to have a tumorigenic effect also in breast cancer, lung cancer, and is also reported to be associated with poor survival outcome in prostate cancer." (PMID 34439361, 2021). "BRE exerts antitumor and antimetastasis roles by regulating the PAQR4‐mediated PI3K/Akt pathway in prostate cancer." (PMID 37584258, 2023). "Meanwhile, circNOLC1 is enhanced by NF-kB, and induces prostate cancer development by miR-647/PAQR4 axis." (PMID 34789263, 2021). "Prior research indicates that PAQR4 may serve as a promising therapeutic target for various tumors, including ovarian cancer, prostate cancer, and renal papillary cell carcinoma." (PMID 40978552, 2025). "Furthermore, it modifies the PAQR4-mediated PI3K/AKT pathway in prostate cancer and limits tumor growth and metastasis." (PMID 37316553, 2023). "Notably, breviscapine has been discovered to modulate the PAQR4-mediated PI3K/AKT pathway while inhibiting prostate cancer cell growth and metastasis." (PMID 37316553, 2023). "In previous studies, it has been shown that PAQR4 promotes tumorigenesis and metastasis via the PI3K/AKT pathway in hepatocellular carcinoma and prostate cancer." (PMID 36609413, 2023). "PAQR4-mediated PI3K/Akt pathway was also reported to increase tumorigenesis and metastasis in prostate cancer." (PMID 36481756, 2022).
breast carcinoma (7 papers, 2020 to 2024). "A recent study showed that PAQR4 is expressed at higher levels in the tumour tissue of patients with breast cancer than in corresponding normal tissues and that its expression correlates negatively with patient survival." (PMID 39464509, 2024). "In breast cancer, PAQR4 was discovered to be located in the Golgi apparatus, where it reduces cytotoxicity and generates S1P to aid cell development." (PMID 36609413, 2023). "Studies in NSCLC6 and breast cancer suggested PAQR4 developed a tumorigenic effect by regulating the ubiquitination and degradation of CDK416." (PMID 36481756, 2022). "Meanwhile, the PAQR4 high expression group showed worse relapse-free survival in lung and breast cancers." (PMID 36573110, 2022). "Research has shown that PAQR4 is highly expressed in breast carcinoma and activates antiapoptotic ceramidase to promote tumor proliferation." (PMID 36573110, 2022). "Also, the knockdown of PAQR4 in human breast cancer cell lines SUM159 and MCF7 suppressed cell proliferation." (PMID 39464509, 2024). "The PAQR4 high expression group had a worse DFS for breast cancer." (PMID 36573110, 2022).
non-small cell lung carcinoma (7 papers, 2020 to 2024). A group of at least three distinct histological types of lung cancer, including non-small cell squamous cell carcinoma, adenocarcinoma, and large cell carcinoma. "PAQR4 was discovered to disrupt the interaction between Nrf2 and Keap1 in non-small-cell lung cancer (NSCLC), preventing Nrf2 protein degradation and thereby decreasing the sensitivity of malignant cells to chemotherapy." (PMID 36609413, 2023). "PAQR4 promotes cell proliferation and metastasis in both non-small-cell lung cancer 42 and gastric cancer." (PMID 32913470, 2020). "Moreover, PAQR4 promoted cell growth, metastasis, and chemoresistance in non-small-cell lung cancer." (PMID 33490086, 2020). "In non-small cell lung cancer (NSCLC), PAQR4 was reported to promote tumor cell proliferation and metastasis, and also contribute to chemotherapy resistance." (PMID 36481756, 2022).
lung adenocarcinoma (2 papers, 2020 to 2022). A carcinoma that arises from the lung and is characterized by the presence of malignant glandular epithelial cells. "OS was significantly worse in the PAQR4 high expression group: BLCA, KIRC, KIRP, LIHC, LUAD (lung adenocarcinoma), OV, and SARC, and PAQR4 was a risk factor affecting the prognosis of these tumors." (PMID 36573110, 2022).
acute lymphoblastic leukemia (1 paper, 2022). Leukemia with an acute onset, characterized by the presence of lymphoblasts in the bone marrow and the peripheral blood. "Poor OS occurred with high PAQR4 expression in 11 tumor types (LGG (brain lower grade glioma), LUAD, KIRP, KIPAN (pankidney cohort), LIHC, BLCA, SKCM-M (skin cutaneous melanoma-metastasis), MESO, PAAD, LAML (acute myeloid leukemia), and ALL (acute lymphoblastic leukemia))." (PMID 36573110, 2022).
bladder cancer (1 paper, 2022). "Cell proliferation, migration, and invasion of bladder cancer and renal clear cell carcinoma cell lines were significantly decreased after the knockdown of PAQR4." (PMID 36481756, 2022). "QRT-PCR results showed that PAQR4 mRNA level was significantly higher in bladder cancer tissues (75%) than in adjacent normal tissues (P-value<0.05)." (PMID 36481756, 2022). "The results of immunohistochemistry showed that PAQR4 was highly expressed in cancer tissues of patients with bladder cancer and renal clear cell carcinoma." (PMID 36481756, 2022). "Moreover, PAQR4 was highly expressed in bladder cancer and renal clear cell carcinoma tissues and cell lines." (PMID 36481756, 2022). "Bladder cancer cell lines T24 and renal clear cell carcinoma cell line 786-O cells with high levels of PAQR4 mRNA and protein expression were further selected to be transfected with siRNA to target PAQR4, and the knockdown efficiency was verified by qRT-PCR and western blot." (PMID 36481756, 2022).
brain cancer (1 paper, 2022). A primary or metastatic malignant neoplasm affecting the brain. "The high PAQR4 expression group had worse OS in lung, bladder, and brain cancers." (PMID 36573110, 2022).
colon adenocarcinoma (1 paper, 2022). "PAQR4 was significantly correlated with NEO, including positive correlations in three tumors (COADREAD (colon adenocarcinoma/rectum adenocarcinoma esophageal carcinoma), UCEC, and THYM) and negative correlations in two tumors (GBM and PCPG)." (PMID 36573110, 2022).
hepatic diseases (1 paper, 2025). "PAQR4 regulates adipose ceramide levels; the dysregulation of PAQR4 leads to an accumulation of lipotoxic ceramide species, particularly long-chain ceramides, correlated with the increased risks of developing metabolic and hepatic diseases." (PMID 40564914, 2025).
liver cancer (1 paper, 2023). An epithelial or non-epithelial malignant neoplasm that arises from the liver. "In the diethylnitrosamine (Den)-induced mouse model of liver cancer, we also observed high expression levels of PAQR4 and found that it was correlated with shorter overall survival and disease-free survival rates." (PMID 36609413, 2023).
mesothelioma (1 paper, 2022). A usually malignant and aggressive neoplasm of the mesothelium which is often associated with exposure to asbestos. "PAQR4 was differentially expressed in tumor cell lines and was exceptionally high in SCLC (small cell lung cancer) and low in MESO (mesothelioma) cell lines." (PMID 36573110, 2022).
cancer (9 papers, 2020 to 2025). A tumor composed of atypical neoplastic, often pleomorphic cells that invade other tissues. "We will further explore the specific mechanisms underlying PAQR4 involvement in chemotherapy resistance in different cancers, which is important for guiding personalized clinical drug decisions." (PMID 36573110, 2022). "The high expression of PAQR4 was closely associated with high tumor stage, immune cell infiltration, tumor mutation burden, and microsatellite instability in different cancer types." (PMID 36481756, 2022). "These epigenetic alterations may cause dysregulation of PAQR4 in many cancers and can act as risk markers for tumors." (PMID 36573110, 2022). "PAQR4 protein plays a major role in cancer cell proliferation, migration, invasion, and epithelial-mesenchymal transition, as well as in the suppression of apoptosis." (PMID 39464509, 2024). "By contrast, GEPIA data for tissues derived from three different stages of OC show that expression of this gene decreases with increasing cancer stage; however, expression of PAQR4 in OC tissues was highly variable." (PMID 39464509, 2024). "Our analysis across pancancer provides new perspective into the study of PAQR4 in cancer, uncovers immunological and epigenetic mechanisms, and provides new strategies for the early diagnosis and immunotherapy of tumors." (PMID 36573110, 2022). "Our research provided a significant correlation between PAQR4 expression and the tumors purity in 18 cancers, especially in THYM and BLCA, where higher PAQR4 was associated with lower tumor purity." (PMID 36573110, 2022). "In BLCA, KIRP, LUSC, and MESO, we observed that PAQR4 high expression was enriched in this pathway, and PAQR4 high expression in all these cancers suggested a poor prognosis." (PMID 36481756, 2022). "In summary, PAQR4 has the potential value as a biomarker for determining prognosis in a variety of cancers." (PMID 36481756, 2022). "Our study systematically analyzed the relationship between PAQR4 and pan-cancer and the role of immunity." (PMID 36481756, 2022). "In this study, PAQR4 expression was unambiguously upregulated in 18 cancers, which was consistent with the results of existing studies on individual cancers." (PMID 36481756, 2022). "Analysis of the GSEA enrichment results for PAQR4 showed that in pan-cancer, PAQR4 high expression was commonly enriched in antigen processing and presentation pathway." (PMID 36481756, 2022). "Using the TISIDB immunological website, we examined the relationship between PAQR4 and immune subtypes in several cancers." (PMID 36573110, 2022). "We analyzed the relation between PAQR4 and three immunomodulators in pan-cancer using the TISIDB database." (PMID 36481756, 2022). "In this study, the expression of PAQR4, correlations with clinical prognosis, immune situation, and its potential molecular functions and mechanisms in pan-cancer were explored by bioinformatics analysis." (PMID 36481756, 2022). "In the future, we will prospectively investigate PAQR4's function and attempt to develop and test novel antitumor immunotherapeutic agents targeting PAQR4 to enable more precise treatment of malignant tumor patients." (PMID 36573110, 2022). "Eight cancers with significant PAQR4 overexpression and prognostic significance were selected to summarize their KEGG pathway analysis and GO functional annotation results." (PMID 36481756, 2022). "A significant role for PAQR4 in tumor immunity is evident in these studies, as well as its potential role in cancer diagnosis, prognosis, and treatment precision." (PMID 36573110, 2022). "The expression of PAQR4, its correlations with clinical characteristics, prognosis, immune system, and its potential molecular functions and mechanisms in pan-cancer were systematically accessed through public databases." (PMID 36481756, 2022).
cancer (continued). "To investigate the potential roles of PAQR4 in tumorigenesis, we examined its expression in various cancer types using gene expression profiling interactive analysis 35, and found that PAQR4 is highly expressed in many cancer types." (PMID 32206121, 2020). "Thus, PAQR4 influences tumorigenesis by participating in multiple gene alterations and has the potential to be an important marker for cancer immunotherapy and prognosis." (PMID 36573110, 2022). "The expression level of PAQR4 in 33 cancers was further sorted from high to low." (PMID 36481756, 2022). "Consequently, we infer that PAQR4 is a novel oncogene involved in multiple pathways promoting cancer development and is a potential prognostic and therapeutic pancancer biomarker." (PMID 36573110, 2022). "Our study is for the first time to analyze the role of PAQR4 across diverse cancer types." (PMID 36481756, 2022). "PAQR4 alterations in different cancers were analyzed using cBioPortal." (PMID 36573110, 2022). "The results proved that PAQR4 expression was significantly elevatory in most cancer types." (PMID 36573110, 2022). "Since the tumor immune microenvironment (TIME) which could be influenced by multiple factors has been gradually recognized as a key contributor to cancer progression, we were full of curiosity about the relevance of PAQR4 and tumor immunity." (PMID 36481756, 2022). "PAQR4 has been shown to play a role in several types of cancer." (PMID 36481756, 2022). "We analyzed the association of PAQR4 expression with TMB and MSI in pan-cancer." (PMID 36481756, 2022). "The activity of PAQR4 in cancer tissues was generally higher than that in normal tissues." (PMID 36481756, 2022). "In the correlation analysis of TMB and MSI, the vast majority of tumor TMB and MSI were positively correlated with PAQR4 expression, suggesting that immunotherapy and chemotherapy targeting PAQR4 in cancer treatment might have great significance." (PMID 36481756, 2022). "PAQR4 gene alterations occurred in 1.1% of the patients with cancer." (PMID 36573110, 2022). "The gene PAQR4 is down-regulated under Al-10-49 and Tamoxifen apoptotic treatments, rosemary, Withaferin A and Eusynstyelamide B nutrigenomics treatments, while it is up-regulated in 21 different cancer types." (PMID 34439361, 2021). "Especially, PAQR3, the closest homologue of PAQR4, has been recently discovered as a novel tumor suppressor deregulated in various types of human cancers including colon cancer, gastric cancer, bladder cancer, liver cancer, osteosarcoma, breast cancer, and laryngeal squamous cell carcinoma 25-30." (PMID 32206121, 2020). "Furthermore, depleting PAQR4 increases the sensitivity of these cancer cells to chemotherapy." (PMID 39464509, 2024). "PAQR4 may serve as a potential prognostic biomarker in a variety of cancers." (PMID 36481756, 2022). "However, current studies of PAQR4 in tumors have been limited to a specific type of cancer." (PMID 36573110, 2022). "Tgm2 and Paqr4 may provide suppressive effects in some aggressive cancer cells." (PMID 34202278, 2021). "However, whether PAQR4 is involved in antioxidant or drug resistance functions in cancers remains elusive." (PMID 32206121, 2020). "PAQR4 inhibits SKP2-mediated ubiquitination of CDK4 by competitive binding to the binding site, contributing to cancer cell proliferation and carcinogenesis." (PMID 36609413, 2023). "The function of PAQR4 in BLCA and KIRC cancer cell lines was briefly verified by cellular experiments for the first time." (PMID 36481756, 2022). "Using the GSCA website, we further examined the connection between PAQR4 expression and CNV in other cancers." (PMID 36573110, 2022). "Although PAQR4 is highly expressed in many cancers, the research on PAQR4 is still limited, and the detailed mechanism of the role of PAQR4 in cancer has not been elaborated yet." (PMID 36481756, 2022).
cancer (continued). "In addition, the relations between the expression of PAQR4 and immunoinhibitors, immunostimulators, and MHC molecules in pan-cancer were analyzed by the TISIDB database." (PMID 36481756, 2022).